TLR9 (toll like receptor 9)
Diseases named in the same sentence as TLR9 in open-access papers (continued):
Sharing a sentence is not in itself a finding about the gene and the disease.
alcoholic cirrhosis (2 papers, 2010 to 2012). "Moreover, stimulation of B cells through Toll-like receptor 9 (TLR-9) has been implicated in causing hyperimmunoglobulinemia in patients with alcoholic cirrhosis." (PMID 22229098, 2012). "Also, overexpression of TLR9, TLR4, and TLR2 was associated with impaired neutrophil function in alcoholic liver cirrhosis." (PMID 20827314, 2010).
alcoholic hepatitis (2 papers, 2021 to 2024). Acute hepatitis resulting from ingestion of alcohol. "The activation of TLR9 by mtDNA triggers a pro-inflammatory response, leading to neutrophilic inflammation, which exacerbates liver injury and promotes the progression of alcoholic hepatitis." (PMID 39765821, 2024). "In an alcoholic hepatitis mice model, where oxidative stress exists due to the generation of ROS in the liver, EVs containing mtDNA released by hepatocytes have been shown to activate Toll-like receptor 9 (TLR9), which is highly expressed in immune cells." (PMID 39765821, 2024).
alcoholic liver diseases (2 papers, 2015 to 2021). A disorder caused by damage to the liver parenchyma due to alcohol consumption. "A potential mechanism involving TLR9 has been shown to cause increased IgA levels in patients with alcoholic liver disease, and TLR-7-mediated plasma cell activation has also been reported to induce Ig synthesis." (PMID 25826264, 2015).
angioimmunoblastic T-cell lymphoma (2 papers, 2020 to 2025). A mature T-cell non-Hodgkin lymphoma, characterized by systemic disease and a polymorphous infiltrate involving lymph nodes and extranodal sites. "However, the clinical relevance of TLR9 and PD-L1 expression in angioimmunoblastic T-cell lymphoma (AITL) has not been evaluated." (PMID 31892973, 2020).
astrocytoma (2 papers, 2014). "Furthermore, synthetic TLR9-ligands (CpG-sequence containing oligonucleotides) have been demonstrated to stimulate the in vitro invasion of TLR9-expressing cancer cells, including astrocytoma and glioblastoma cells." (PMID 24959259, 2014).
Ataxia (2 papers, 2020 to 2023). Ataxia refers to impaired coordination of voluntary muscle movement. "In the bivariate analysis between the factors and TLR9 polymorphisms, carriers of a TLR9 variant genotype (CT or CC) had a lower risk of ataxia (OR, 0.22; 95% Cl, 0.06–0.84; p = 0.029) and other neurological sequelae (OR, 0.15; 95% Cl, 0.02–1.26; p = 0.049) at the time of discharge." (PMID 32967147, 2020).
bacterial pneumonia (2 papers, 2010 to 2012). Acute infection of the lung parenchyma caused by bacteria (e.g., Streptococcus pneumoniae, Haemophilus influenzae, Chlamydia pneumoniae, Mycoplasma pneumoniae, and Legionella pneumophila). "We have reported that only class C CpG ODNs can effectively activate TLR9 in a manner that synergizes with TLR2/6 to protect against bacterial pneumonia." (PMID 22299046, 2012).
brucellosis (2 papers, 2025). Brucellosis is a bacterial infection that spreads from animals to people via unpasteurized dairy products or by exposure to contaminated animal products or infected animals. "Several genes of the SLAM family (SLAMF1, SLAMF7, and SLAMF8) were overexpressed in acute but not in chronic brucellosis patients, unlike stable TLR9 gene expression." (PMID 40231463, 2025).
childhood asthma (2 papers, 2013 to 2025). "Toll-like receptor 2, toll-like receptor 6, toll-like receptor 9, and toll-like receptor 10 appear to have some association with childhood asthma in Caucasians." (PMID 23496969, 2013). "For instance, the TLR9 rs187084 polymorphism is associated with the control of childhood bronchial asthma to some extent, and the overall TLR9 SNP profile is significantly correlated with susceptibility to childhood asthma." (PMID 40672946, 2025). "For TLR9, rs187084 showed a positive association with childhood asthma, but not in all studies." (PMID 23496969, 2013).
cholangiocarcinoma (2 papers, 2021 to 2023). A carcinoma that arises from the intrahepatic biliary tree (intrahepatic cholangiocarcinoma) or from the junction, or adjacent to the junction, of the right and left hepatic ducts (hilar cholangiocarcinoma). "In our study, we demonstrate that both TLR7 and TLR9 expression are associated with a favorable prognosis in our cohort of cholangiocarcinoma patients." (PMID 34573939, 2021). "TLR-9 inhibition with chloroquine inhibited in vitro growth of cholangiocarcinoma and in xenografts." (PMID 37895152, 2023). "A similar pattern was seen in cholangiocarcinoma, where TLR-9 was overexpressed, yet it was absent in normal biliary tracts." (PMID 37895152, 2023).
chronic hepatitis C (2 papers, 2009 to 2020). "The TLR9 compound SD-101 is being studied as an adjuvant for chronic hepatitis C (NCT00823862)." (PMID 33679711, 2020).
colon adenocarcinoma (2 papers, 2020 to 2023). "Here, we have described the superior antitumor efficacy of co-delivering docetaxel chemotherapy and TLR9 agonist CpG on sHDL nanoparticles to MC-38 colon adenocarcinoma tumors when compared to docetaxel alone." (PMID 32150841, 2020). "In diffuse large B-cell lymphoma cells and colon adenocarcinoma cells, NETs could exert pro-tumorigenic effects by activating TLR9 and its downstream signaling through pathways such as NF-kB and MAPK." (PMID 36050539, 2023). "We hypothesize that sHDL encapsulating docetaxel chemotherapy and decorated with Toll-like receptor 9 (TLR9) agonist CpG oligonucleotide will ensure effective delivery to colon adenocarcinoma tumors, leading to suppressed tumor growth and long-term survival as compared to monotherapy delivery." (PMID 32150841, 2020).
corneal ulcer (2 papers, 2013 to 2015). Area of epithelial tissue loss from corneal surface; associated with inflammatory cells in the cornea and anterior chamber. "We found that neutrophils comprised >90% cells in corneal ulcers, and that there was elevated expression of TLR2, TLR4, TLR5 and TLR9, the NLRP3 and NLRC4 inflammasomes and the ASC adaptor molecule." (PMID 23750216, 2013).
cutaneous lupus erythematosus (2 papers, 2022 to 2025). An autoimmune disorder that manifests as different lupus-specific skin disorders; it can occur with systemic lupus erythematosus, or as a singular disease. "Hydrochloroquine also reduces type I IFN production of TLR7 or TLR9 activated pDCs in patients with SLE and also inhibits TLR9 activation-induced type I IFN production by pDCs of cutaneous lupus erythematosus patients." (PMID 36142877, 2022). "Furthermore, HCQ levels in the blood of patients with cutaneous lupus erythematosus correlated negatively with the IFNα-producing capacity of their pDCs upon TLR9 stimulation, with a weaker correlation observed upon TLR7/8 stimulation." (PMID 40746538, 2025). "pDCs isolated from cutaneous lupus erythematosus and SLE patients administered HCQ had significantly lower IFNα production upon TLR7 or TLR9 stimulation compared with patients not receiving HCQ." (PMID 40746538, 2025).
cutaneous T-cell lymphoma (2 papers, 2015 to 2023). "For example, the TLR7 and TLR9 agonists are used to treat skin cancer and cutaneous T-cell lymphoma, and TLR9 agonists are being tested in clinical trials against NSCLC." (PMID 26220208, 2015).
depression (2 papers, 2021 to 2025). "Previous works have described how TLR3, TLR4, TLR5, TLR7, TLR8, and TLR9 mRNA expressions in peripheral blood mononuclear cells seem to be increased in patients with depression." (PMID 34819919, 2021).
diabetic nephropathy (2 papers, 2022 to 2023). "The effect of TLRs on the maintenance of diabetic nephropathy (DN) and resistance to infection has been investigated; however, the detailed effects of TLR9 on DN development remain elusive." (PMID 35120573, 2022).
dry eye (2 papers, 2022). "In the ocular surface of patients with dry eye, increased expression levels of TLR9, MyD88, INF-α, and IFN-β have been detected." (PMID 35812407, 2022). "The role of TLR9 in the inflammatory response of dry eye indicates that DNA may initiate immune-inflammatory responses in dry eye." (PMID 35812407, 2022). "Toll-like receptor 9 (TLR9) is a PRR and has been demonstrated to participate in dry eye by recognizing dsDNA." (PMID 35812407, 2022).
eosinophilia (2 papers, 2014 to 2022). "Eosinophilia in TLR9-/- infected mice could be associated to the Th2 profile induced by C. gattii." (PMID 36145419, 2022). "Analysis of cell influx into the BAL showed that both TLR agonists significantly reduced lung eosinophilia (TLR7 agonist by 55% and TLR9 agonist by 91%)." (PMID 24618687, 2014).
Fulminant hepatitis (2 papers, 2017 to 2020). Acute hepatitis complicated by acute liver failure with hepatic encephalopathy occurring less than 8 weeks after the onset of jaundice. "The newly established anti-TLR9 monoclonal antibody (mAb) called NaR9 has a protective action against fulminant hepatitis developed in response to the over-activated TLR9 upon recognizing self-DNA and inducing systemic cytokine storm." (PMID 33643304, 2020).
gingivitis (2 papers, 2019 to 2024). A disorder involving inflammation of the gums; may affect surrounding and supporting structures of the teeth. "TLR9 protein was clearly observed in gingivitis and cariogenic biofilms but again mRNA levels were below detection level." (PMID 31448244, 2019).
Glucose intolerance (2 papers, 2025). Glucose intolerance (GI) can be defined as dysglycemia that comprises both prediabetes and diabetes. "Paradoxically, TLR9-deficient mice show increased weight gain, severe glucose intolerance, and enhanced adipose tissue inflammation when fed a high-fat diet, indicating that TLR9 signaling may have protective functions in regard to metabolic regulation." (PMID 41425575, 2025).
helminth infection (2 papers, 2017 to 2025). "Among these, ZEB1 has been described during helminth infection, where TLR9 stimulation increased ZEB1 expression in cDC1 dendritic cells." (PMID 40871238, 2025).
Hepatitis C (2 papers, 2009 to 2011). "Human T-cells purified from HIV and from Hepatitis C patients were also shown to express TLR7 and/or TLR9." (PMID 21253574, 2011).
Herpes simplex infection (2 papers, 2015 to 2021). "For example, exogenous stimulation of TLR5 and TLR9 has been assessed in mouse models of enteric Salmonella and vaginal Herpes simplex infections, respectively." (PMID 26793623, 2015).
intracerebral hemorrhage (2 papers, 2022 to 2024). A cerebrovascular disorder characterized by bleeding into one or both cerebral hemispheres including the basal ganglia and the cerebral cortex. "An experimental study using the intracerebral hemorrhage model showed that activation of TLR-9 increased Iba-1 and HO-1 positive cells with enlarged cell bodies around the hematoma thus facilitating macrophage/microglial phagocytosis." (PMID 39839349, 2024).
irritable bowel syndrome (2 papers, 2017 to 2022). Irritable bowel syndrome (IBS) is a chronic functional condition of the lower gastrointestinal (GI) tract characterized by abdominal pain or discomfort and disordered bowel habit (diarrhea, constipation, or fluctuation between the two). "Supporting our results, patients with irritable bowel syndrome present an overexpression of TLR9." (PMID 35670957, 2022).
Klebsiella pneumonia (2 papers, 2010 to 2014). An pneumonia caused by infection with Klebsiella. "In that study, TLR9-/- mice displayed significantly increased mortality following intra-tracheal infection with Klebsiella pneumonia." (PMID 24595157, 2014). "We and others have previously shown that both TLR4 and TLR9 play a critical role in host defense during Klebsiella pneumonia." (PMID 20360853, 2010).
leukocytosis (2 papers, 2020 to 2025). "In PV, ON-GNPs targeting TLR9, IRF7, and IL-8 pathways may reduce thrombotic risk and leukocytosis, while in ET, they could mitigate platelet activation and chronic inflammation." (PMID 40016346, 2025).
leukopenia (2 papers, 2015). "As previously reported, sustained TLR9 stimulation induced leukopenia with lower amounts of CD11b and CD3 positive cells in TLR9 stimulated control mice." (PMID 26461521, 2015). "It is worth mentioning that the deletion of the TLR2, TLR9 or MyD88 genes did not seem to affect the irinotecan-induced cytotoxic effects because the leukopenia was still observed." (PMID 26440613, 2015).
macrophage activation syndrome (2 papers, 2023 to 2025). A complication of rheumatic disease that is caused by excessive activation and uncontrolled proliferation of T lymphocytes and well-differentiated macrophages. "Chronic signaling through TLR7 and TLR9 is also associated with driving the differentiation of inflammatory hemophagocytic cells, leading to anemia and thrombocytopenia observed in conditions such as macrophage activation syndrome (MAS) and malaria." (PMID 40510367, 2025).
meningococcal infection (2 papers, 2014 to 2020). Infections with bacteria of the species neisseria meningitidis. "On the other hand, Neisseria meningitidis infection inhibits HIV replication by inducing IFN responses through TLR9." (PMID 24404168, 2014). "The effect of the TLR9 SNP rs187084 has not yet been reported for pneumococcal or meningococcal infections, although it is associated with other bacterial infections." (PMID 32967147, 2020).
metastatic tumors (2 papers, 2025). "While intratumoral injection of TLR9 agonists (such as MGN1703 and IMO-2125) has shown preliminary clinical efficacy in treating superficial tumors, repeated administration remains clinically challenging, particularly for deep-seated or metastatic tumors." (PMID 41291120, 2025).
myxoma (2 papers, 2012 to 2014). A benign soft tissue neoplasm characterized by the presence of spindle and stellate cells, lobulated growth pattern, and myxoid stroma formation. "Strikingly, WT vaccinia infection blocks type I IFN/TNF induction in response to myxoma, TLR9 agonist CpG, or TLR7 agonist imiquimod." (PMID 22606294, 2012). "In contrast, myxoma-induced type I IFN induction was abolished in MyD88−/−, or TLR9−/− pDCs, but modestly reduced in TLR7−/− pDCs." (PMID 22606294, 2012). "This protein is also able to counteract the detection of myxoma virus and CpG-ODN by TLR9." (PMID 25171368, 2014).
neutropenia (2 papers, 2011 to 2024). A decrease in the number of neutrophils found in the blood. "Therefore, it is possible that the vaccine induced neutropenia through TLR9." (PMID 22003411, 2011).
ocular toxoplasmosis (2 papers, 2015 to 2017). Ocular toxoplasmosis is an infection in the eye caused by the parasite, Toxoplasm a gondii. "Regarding TLR9 polymorphisms, it was reported that the C allele at the TLR9 1635 G>A SNP correlated with toxoplasmic retinochoroiditis in Brazilian children with ocular toxoplasmosis." (PMID 26254559, 2015). "Taking into account TLR genetic changes, possibly involved in the development of T. gondii infections, the TLR9 1635 A>G single nucleotide polymorphism (SNP) was reported to be associated with toxoplasmic retinochoroiditis among Brazilian children with ocular toxoplasmosis." (PMID 26254559, 2015). "Noting this association for TLR9 in the NCCCTS, we also have replicated the importance of TLR9 in susceptibility to ocular toxoplasmosis in a cohort in Brazil32." (PMID 28904337, 2017).
otitis (2 papers, 2012 to 2021). "The same group also reported a significantly lower expression of TLR9 in otitis-prone group than in non-otitis-prone group." (PMID 22662179, 2012). "Another study reported that TLR9 mRNA expression was lower in middle ear fluid collected from OME patients in an otitis-prone group than in non-otitis–prone patients." (PMID 34360632, 2021).
parasite (2 papers, 2018 to 2023). "Thus, the role of TLR-9 in the control of parasite infections is not unequivocal and may result in either protective or susceptibility responses depending on the Leishmania species." (PMID 37111420, 2023).
Parvovirus Infection (2 papers, 2013 to 2022). "Our work also points to TLR-9 as the PRR sensing rodent parvovirus infections in hPBMCs." (PMID 23383065, 2013). "However, since a residual production of antiviral cytokines persisted in the infected cultures despite the TLR-9 pathway inhibition, they further suggest that additional sensors might be activated in hPBMCs upon rodent parvovirus infections." (PMID 23383065, 2013).
pneumococcal meningitis (2 papers, 2019 to 2021). An acute purulent infection of the meninges and subarachnoid space caused by Streptococcus pneumoniae, most prevalent in children and adults over the age of 60. "Pre-treatment with 100 μg CpG ODN did not protect TLR9−/− mice against pneumococcal meningitis (P = 0.53, log-rank test)." (PMID 33531028, 2021).
polycythemia vera (2 papers, 2017 to 2022). "The genotypes C/T (TLR5 R392StopCodon) and T/T (TLR9 -1486C/T) appear to be risk factors for Pv-infection (TLR5: C/C vs. C/T OR = 2.1 [95% CI: 1.1–4.5, p = 0.031]; TLR9: C/C vs. T/T OR = 1.9, [95% CI: 1.2–3.2, p = 0.01]; TLR9: C/C vs. C/T+T/T OR = 1.6, [95% CI: 1.1–2.5, p = 0.024])." (PMID 28850598, 2017). "In that study, they found that TLR9-1486 CT may be associated with a lower susceptibility to developing polycythemia vera (PV), and in the haplotype frequency analysis, TLR9-1237T/-1486C was less common in men compared to controls, as well as in men negative for JAK V617F." (PMID 36076988, 2022).
Primary Biliary Cirrhosis (2 papers, 2013 to 2023). "rs352140 is associated with higher TLR9 expression in patients with primary biliary cirrhosis, an autoimmune liver disease, and infected by hepatitis virus." (PMID 37139337, 2023).
prion disease (2 papers, 2010 to 2024). A transmissible disease that is caused by a protein that is able to induce abnormal folding of normal cellular proteins, leading to characteristic spongiform brain changes, which are associated with neuronal loss without an inflammatory response. "Notably, previous studies have linked TLR9 expression to prion disease progression, as evidenced by responses to synthetic oligodeoxynucleotides." (PMID 38698886, 2024). "It has been suggested that TLR9 expression may be linked to the progression of prion diseases." (PMID 20706642, 2010). "Our data revealed that the TLR2 and TLR9 subfamilies exhibited increased expression during the pathogenesis of prion disease." (PMID 38698886, 2024). "Furthermore, treatment with synthetic oligodeoxynucleotides that contain cytosine phosphate guanosine (CpG-ODN) motifs, known to bind to TLR9, have been suggested as possible treatment for prion diseases in a mouse model, by delaying the disease onset." (PMID 20706642, 2010).
renal carcinoma (2 papers, 2011 to 2012). A carcinoma arising from the epithelium of the renal parenchyma or the renal pelvis. "The favourable influence of TLR9 expression on the course of the disease may be based on the immunologic response generated to the renal carcinoma cells." (PMID 21929816, 2011). "Our findings thus suggest that the lack of TLR9 confers aggressive behaviour of renal carcinoma cells." (PMID 21929816, 2011).
rhinitis (2 papers, 2012 to 2019). An inflammation of the mucous membrane lining the nose, usually associated with nasal discharge. "This study indicates that TLR4 and TLR9 show a different pattern of expression in different phenotypes of rhinitis, possibly related to the type and severity of the disease." (PMID 22577387, 2012). "This study shows that TLR4 and TLR9 are differently expressed in the nasal mucosa of healthy subjects and of the major rhinitis phenotypes." (PMID 22577387, 2012). "The aim of the present study was to investigate the expression of TLR4 and TLR9 in the healthy and inflammatory nasal mucosa of different rhinitis phenotypes, by means of confocal analysis on paraffin sections of the inferior turbinates." (PMID 22577387, 2012).